MTOR (mechanistic target of rapamycin kinase)
Diseases named in the same sentence as MTOR in open-access papers (continued):
Sharing a sentence is not in itself a finding about the gene and the disease.
pulmonary fibrosis (continued). "Immunohistochemistry and Western blotting were performed to observe changes in proteins related to pulmonary fibrosis (α-smooth muscle actin (α-SMA) and matrix metalloproteinase 12 (MMP12)) and autophagy (P62 and mechanistic target of rapamycin (mTOR))." (PMID 38361765, 2024). "Overall, the results suggested that STX11-SNAP25 interaction significantly inhibited lung fibrosis by promoting fibroblast autophagy and suppressing fibroblast activation via blocking the PI3K/ATK/mTOR signaling pathway." (PMID 39523374, 2024). "Lnc-TUG1 promotes pulmonary fibrosis progression via up-regulating CDC27 and activating PI3K/Akt/mTOR pathway." (PMID 39133718, 2024). "Various signaling pathways regulate pulmonary fibrosis, including the TGF-β, Notch, Wnt, Hedgehog, and mTOR pathways." (PMID 39450276, 2024). "For example, nintedanib treating idiopathic pulmonary fibrosis can reduce the expression of proinflammatory factors IL-1β, IL-6, and TNF-ɑ by downregulating the PI3K/Akt/mTOR pathway." (PMID 39108701, 2024). "This may have wider implications for human health, as a growing body of literature has suggested that mTOR has an important role in the pathogenesis of pulmonary diseases including pulmonary arterial hypertension, chronic obstructive pulmonary disease, and idiopathic pulmonary fibrosis." (PMID 38127441, 2023). "Mammalian targets of Rapamycin (mTOR) and phosphoinositide 3-kinase (PI3K) promote type 2 cytokine-activated macrophage polarization and the development of pulmonary fibrosis." (PMID 38162655, 2023). "It is the first study to systematically investigate the relationship between the anti-pulmonary fibrosis mechanism of nintedanib and the PI3K/Akt/mTOR signaling pathway." (PMID 37160579, 2023). "Studies related to BLM-induced pulmonary fibrosis with celastrol as a treatment exploit the pathways involving Nrf2/Keap1- and PI3K/Akt-mediated mTOR expressions." (PMID 37772226, 2023). "The mTOR inhibitor, sirolimus, inhibits fibrocyte CXCR4 expression, reducing fibrocyte traffic and attenuating lung fibrosis in animal models." (PMID 36853800, 2023). "In pulmonary fibrosis, TGF‐β‐induced differentiation of human lung fibroblasts to fibrogenic myofibroblasts is repressed by inhibiting the PI3K/AKT/mTOR pathway." (PMID 36869852, 2023). "Protein kinase B (PKB, also known as AKT)/mechanistic target of rapamycin (mTOR) pathway serves as one of the most important pathways contributing to the activation of EMT, playing an essential role in the progression of lung fibrosis." (PMID 35707275, 2022). "A recent study has found that activation of the mTOR pathway in lung epithelial cells promotes epithelial–mesenchymal transition (EMT) and lung injury, leading to acceleration of pulmonary fibrosis." (PMID 36267283, 2022). "Kawarazin ameliorates Beclin1-induced pulmonary fibrosis by increasing miR-193a expression and inhibiting PI3K/Akt/mTOR signaling, thereby increasing autophagy in lung cells." (PMID 36105212, 2022). "A previous study demonstrated that LPS activates the PI3K-Akt-mTOR/PFKFB3 pathway, and promotes the collagen synthesis of lung fibroblasts through aerobic glycolysis to aggravate pulmonary fibrosis." (PMID 33777519, 2021). "Sirolimus, a mTOR (mammalian target of rapamycin) inhibitor, attenuates BLM-induced pulmonary fibrosis in rats." (PMID 33912053, 2021). "The interaction of TGFβ1 with MTORC1 (mTOR and raptor) and MTORC2 (mTOR and rictor), has been explored in other cell types and conditions focusing on pulmonary fibrosis." (PMID 34707569, 2021). "For instance, Sirt1 activation or overexpression can inhibit pulmonary fibrosis in vitro via inactivation of TGF-β1/Smad3 and mTOR signaling." (PMID 34925016, 2021). "RG can also inhibit the TGF-β1-induced activation of mTOR signaling in lung fibroblasts, and exhibited the same results in a BLM-induced lung fibrosis model." (PMID 33671452, 2021).
pulmonary fibrosis (continued). "A wide range of diseases such as cancer, cardiac and pulmonary fibrosis, show dysfunction in the PI3K/Akt/mTOR signaling pathways." (PMID 33375386, 2020). "It found that the deletion of miR-301a alleviated pulmonary fibrosis by targeting TSC1, which negatively regulated its downstream mTOR pathway." (PMID 32585629, 2020). "Collectively, the results suggested that miR-301a activated the mTOR pathway by negatively regulating TSC1 in fibroblasts and promoted the progression of pulmonary fibrosis." (PMID 32585629, 2020). "In this study, PQ treatment stimulated the PI3K/Akt signalling pathway and further increased mTOR activation, decreased Beclin1 and LC3-II expression, inhibited autophagy, and exacerbated PQ-induced pulmonary fibrosis." (PMID 30744607, 2019). "We first demonstrated that mTOR, ZEB1 and ROCK1 was expressed in hyperplastic alveolar epithelial cells of human pulmonary fibrosis lungs." (PMID 25358403, 2014). "Thus, mTOR expression may be related to the prognosis of pulmonary fibrosis." (PMID 25358403, 2014). "The expression of mTOR, ZEB1, and ROCK1 was increased in most of the lung tissues of pulmonary fibrosis patients." (PMID 25358403, 2014). "This study was performed to identify the clinical significance of mTOR, ZEB1, and ROCK1 expression in the lung tissues of idiopathic pulmonary fibrosis and UIP pattern connective tissue disease related interstitial lung disease (CTD-ILD) patients." (PMID 25358403, 2014). "We assessed the clinical significance of mTOR, ZEB1, and ROCK1 expression in human pulmonary fibrosis of usual interstitial pneumonia (UIP) pattern." (PMID 25358403, 2014). "This was the first study to evaluate mTOR, ZEB1, and ROCK1 expression in the lung tissues of pulmonary fibrosis patients." (PMID 25358403, 2014). "For examples, functional studies are needed to identify the role of mTOR, ROCK1, and ZEB1 in the pathogenesis of pulmonary fibrosis." (PMID 25358403, 2014). "Moreover, a study demonstrated that tanshinone IIA attenuates pulmonary fibrosis by simultaneously activating AMPK and inhibiting mTOR signaling." (PMID 41301772, 2025). "A recent study on pulmonary fibrosis has revealed that the alterations in miR-423-5p and its target gene forkhead box p4 (FOXP4) have a significant impact on the expression of the PI3K/AKT/mTOR pathway." (PMID 39479511, 2024). "Macrophages regulate pulmonary fibrosis through various pathways such as NF-kB and PI3K-Akt-mTOR." (PMID 38609879, 2024). "In human bronchial epithelial cells (HBEC3s) an active interaction was found between YAP and mTOR/PI3K/AKT pathway, resulting to increased cell proliferation, migration and polarity, that potentially contribute to development of the idiopathic pulmonary fibrosis." (PMID 38802925, 2024). "Intriguingly, overexpression of miR-29a-3p was marked as an activator of protective autophagy by targeting Akt3/mTOR in transforming growth factor (TGF)-β-treated TC-1 cells, as a model of lung fibrosis, and resulted in amelioration of lung fibrosis and protection of lung epithelial cells." (PMID 39594634, 2024). "Abnormal activation of PI3K/AKT/mTOR pathway is important in fibrotic diseases because mTOR signaling not only regulates cellular autophagy but also pulmonary fibrosis, and inhibition of PI3K/AKT/mTOR signaling pathway can have an anti-pulmonary fibrosis effect." (PMID 37533739, 2023). "In conclusion, our study demonstrates that AMI alleviates pulmonary fibrosis in mice by inhibiting BLM-induced oxidative stress, inflammation, and apoptosis and by reducing EMT and ECM aggregation through inhibition of the PI3K/Akt/mTOR signaling pathway." (PMID 37380638, 2023). "Because PI3K/Akt/mTOR signalling pathway is closely related to autophagy in the process of IPF, we hypothesized that Duvelisib may have a therapeutic role in pulmonary fibrosis." (PMID 36651446, 2023).
pulmonary fibrosis (continued). "Furthermore, HIF, mTOR, TGF-β, and NLRP3 play key roles in respiratory diseases such as cancer, pulmonary fibrosis, and cardiovascular diseases." (PMID 37371940, 2023). "Moreover, the existing research found that metformin exhibited pleiotropic mechanisms for alleviating lung fibrosis, such as NOX4 inhibition, IGF-1 suppression, and mTOR inactivation, and so on." (PMID 36091775, 2022). "Hence, blocking AKT/mTOR pathway has been proposed to be a promising strategy to suppress EMT and combat lung fibrosis." (PMID 35707275, 2022). "In conclusion, EG could improve PM2.5-induced lung fibrosis by decreasing oxidative damage and EMT through AKT/mTOR pathway, which might be a potential candidate for the treatment of PM2.5-induced lung fibrosis." (PMID 35707275, 2022). "Similarly, inducing autophagy by inhibiting mTOR activity in lung fibroblasts with rapamycin reduces cellular α-SMA and fibronectin expression linking autophagy and α-SMA expression with lung fibrosis in Myr-Akt mice." (PMID 31750010, 2019). "However, PI3K/Akt signalling was inhibited by ligustrazin, which decreased mTOR activation, increased Beclin1 and LC3-II protein expression and autophagy, and ameliorated PQ-induced pulmonary fibrosis." (PMID 30744607, 2019). "To further verify mTOR activation during the fibrosis process, we performed immunohistochemical staining with α-SMA and p-S6 antibodies in lungs from a bleomycin-mediated pulmonary fibrosis animal model by day 21 after bleomycin intra-tracheal injection in wild-type C57BL/6J mice." (PMID 26382847, 2015). "Enhancement of autophagy depending or not depending on mTOR inhibition worth to be further investigated in pulmonary fibrosis." (PMID 26382847, 2015). "We studied whether mTOR was involved in the process of pulmonary fibrosis in human IPF lung tissues, an animal model of bleomycin-mediated pulmonary fibrosis in vivo, and during trans-differentiation from fibroblasts to myofibroblasts in vitro." (PMID 26382847, 2015). "Because our patients included some patients with CTD-ILD, further studies involving large numbers of homogeneous IPF patients are warranted to determine whether mTOR and ZEB1 are true prognostic markers of pulmonary fibrosis." (PMID 25358403, 2014). "The mTOR and ZEB1 expression in pulmonary fibrosis patients significantly correlated with the fibrosis score and lung function decline, indicating that it may be related to the prognosis of pulmonary fibrosis." (PMID 25358403, 2014). "To date, there are no published clinical trials testing the efficacy of mTOR inhibition in patients with pulmonary fibrosis; however, there is one case report describing partial remission of IPF in a patient treated with rapamycin." (PMID 21660239, 2011). "In the animal model, low AMPK activity could also be found to promote pulmonary fibrosis, and the metformin as an AMPK agonist could alleviate silica-induced lung inflammation and fibrosis by regulating autophagy through AMPK activation and mTOR inhibition." (PMID 38720270, 2024). "We previously reported that human fibrocyte CXCR4 expression is regulated by the mTOR pathway in vitro and that sirolimus inhibits CXCR4 expression and fibrocyte traffic both in vitro and in experimental animals and attenuates bleomycin-induced pulmonary fibrosis." (PMID 36853800, 2023). "The bleomycin-mediated pulmonary fibrosis model was adopted for analyzing the therapeutic impacts of nintedanib and evaluating whether or not its inhibitory effects on pulmonary fibrosis are through suppressing PI3K/Akt/mTOR pathway." (PMID 37160579, 2023). "Accumulating evidence has also shown that the repression of TGF-β1-induced activation of mTOR signaling in lung fibroblasts, which results in the induction of autophagy and the inhibition of myofibroblast activation and ECM production in mice model of BLM-induced pulmonary fibrosis." (PMID 36267283, 2022).
pulmonary fibrosis (continued). "The Nrf2 signaling pathway, mTOR signaling pathway, TGF-β1 signaling pathway, and NF-κB signaling pathway may be interfered by Rg1, and target myocardial cells, podocytes, thereby preventing renal fibrosis, nerve ischemia perfusion injury, and lung fibrosis." (PMID 35388306, 2022). "PI3K p85 was also proven as miR-503 target, and the activation of PI3Kp85/Akt/mTOR/Snail pathway facilitated the development of EMT and pulmonary fibrosis, overexpression of miR-503 has been shown to inhibit silica-induced pulmonary fibrosis by inactivating that pathway." (PMID 33762949, 2021). "Anti-fibrotic effects of mTOR inhibitors have been extensively reported in patients with hepatic or pulmonary fibrosis and rheumatic diseases; however, to the best of our knowledge, no report has yet discussed the potential effects of mTOR inhibitors on hTM cells." (PMID 34239027, 2021). "Other cancer drugs can lead to pulmonary fibrosis, like bleomycin, taxanes, and biological agents like epidermal growth factor receptor (EGFR) small-molecule tyrosine kinase inhibitors (TKIs), monoclonal antibodies to VEGF, and mammalian target of rapamycin (mTOR) inhibitors." (PMID 26904333, 2016). "Therefore, it is hypothesized that mTOR pathway, ZEB1, and ROCK1 may play a role in the pathogenesis of pulmonary fibrosis." (PMID 25358403, 2014). "Thus, mTOR and ZEB1 expression may be related with the prognosis of pulmonary fibrosis and disease progression." (PMID 25358403, 2014). "However, the role of mTOR in human pulmonary fibrosis has not been evaluated." (PMID 25358403, 2014). "It has been reported that the non-Smad signaling pathways, including PI3K/Akt/mTOR and MAPK signaling pathways, are involved in the formation of pulmonary fibrosis." (PMID 36267283, 2022). "Western blot analysis of lung tissues from mice with bleomycin-induced pulmonary fibrosis with or without PI3K inhibitor treatment showed that p-AKT and p-mTOR levels were decreased after treatment with the inhibitor (in prevent and treatment groups)." (PMID 29079731, 2017). "However, we did not see activation of PKC-δ by TGF-β in IPF lung fibroblasts, suggesting a more prominent role possibly for inhibition of Akt by active site mTOR inhibitors, not PKC-δ, in the inhibition of fibroblast activation and lung fibrosis." (PMID 25162417, 2014). "In conclusion, RG attenuated BLM-induced pulmonary fibrosis in mice, inhibited myofibroblast activation and migration, and induced myofibroblast autophagy and apoptosis to downregulate ECM accumulation by suppressing the TGF-β1/Smad, TGF-β1/non-Smad, and mTOR signaling pathways." (PMID 33671452, 2021).
COVID-19 (140 papers, 2020 to 2026). A disease caused by infection with severe acute respiratory syndrome coronavirus 2. "The meta-analysis also found that using mTOR inhibitors in kidney transplant patients is linked tolower odds of death from COVID-19 compared to other forms of immunosuppression (OR= 0.63, 95% CI 0.48 to 0.83, P= 0.001)." (PMID 40978637, 2025). "While our study provides clear proof-of-concept for myeloid cell-specific mTOR inhibition in infection-associated inflammation, it is limited to studying myeloid cells from COVID-19 patients only." (PMID 40177636, 2025). "Our analysis of the previously published COVID-19 dataset showed that mTOR pathway-associated genes are dysregulated across various immune cell populations, albeit to a greater extent on monocyte subsets in hyperinflammatory conditions." (PMID 40177636, 2025). "In LAM patients, a use of mTOR inhibitors reduced the risk of developing symptoms during COVID-19, including fatigue [OR: 0.18, 95% CI: (0.03, 0.95)], anorexia [OR: 0.30, 95% CI: (0.09, 0.96)], and ageusia [OR: 0.20, 95% CI: (0.06, 0.67)]." (PMID 38956624, 2024). "Multiple intracellular transductions, such as TNF-alpha, mTOR, NF-κB, etc., are implicated in the pathogenesis of COVID-19." (PMID 35992697, 2022). "Our study first shows that the use of mTOR inhibitors when compared with other immunosuppressive regiments was associated with a more favorable outcome of COVID-19 in a cohort of patients." (PMID 35801204, 2022). "MTOR is a key protein in the mTOR pathway that appears to play a crucial role in regulating the immune dysregulation processes underlying COVID-19 in diabetic patients." (PMID 36532549, 2022). "Increased signaling through the mammalian/mechanistic Target of Rapamycin (mTOR) signaling pathway is a common characteristic in all comorbidities associated with a higher risk of mortality by COVID-19." (PMID 36661509, 2022). "In kidney transplant patients, the use of mTOR inhibitors as part of an immunosuppressive regimen is associated with a better prognosis in the case of COVID-19." (PMID 35801204, 2022). "We have chosen to illustrate these details by considering two quite different disease types: cancers that involve mutations on the mammalian target of rapamycin (mTOR) pathway, and coronovirus infections (specifically COVID-19)." (PMID 33313340, 2021). "Hence, we evaluated 24 observational studies with 5,882 kidney transplant patients to assess the associationof mTOR inhibitors with COVID-19 severity and mortality." (PMID 40978637, 2025). "Kidney transplant recipients are at increased risk of severe COVID-19 due to immunosuppression and the impact of mTOR inhibitors onoutcomes remains unclear." (PMID 40978637, 2025). "On the contrary, mTOR inhibitors appear to mitigate the symptoms associated with COVID-19." (PMID 38956624, 2024). "Moreover, Rho GTPases have been linked to additional key metabolic controls such as mTOR signaling pathways, which are specifically upregulated in COVID-19 patients." (PMID 36992700, 2023). "Only a few studies have looked at patients with LAM on mTOR inhibitors to evaluate whether it places patients at greater risk of contracting COVID-19 or if it could have beneficial effects." (PMID 35836441, 2022). "Antiviral drugs commonly used for the treatment of COVID-19 may have several drug–drug interactions, causing increased serum levels of CNIs and mTOR inhibitors." (PMID 33946462, 2021). "In humans, mTOR inhibition has been found to ameliorate some adverse consequences of aging, including low-grade chronic generalized inflammation nicknamed inflammaging, which has been implicated in COVID-19 pathogenesis." (PMID 33343386, 2020). "MTOR inhibitors may prevent excessive immune activation by lowering T cell activation, which would lessen the cytokine storm andsubsequent tissue damage that are frequently linked to severe COVID-19." (PMID 40978637, 2025).